STMN1 (stathmin 1)
Diseases named in the same sentence as STMN1 in open-access papers (continued):
Sharing a sentence is not in itself a finding about the gene and the disease.
prostate carcinoma (21 papers, 2010 to 2025). A carcinoma that arises from epithelial cells of the prostate gland. "High Stathmin 1 expression was also associated with poor overall survival, and survival worsened when prostate cancer metastasized to the liver compared to other organs." (PMID 40723207, 2025). "Studies have shown that STMN1 is highly expressed in various cancers, including gastric, ovarian, and prostate cancers, and its increased expression was associated with resistance of tumor cells to the anti-tumor effects of microtubule inhibitors." (PMID 37165308, 2023). "In prostate cancer cells, low STMN1 expression was observed in highly invasive, EMT-like cells isolated from undifferentiated adenocarcinomas." (PMID 40225568, 2025). "This study investigated Stathmin 1, a protein that regulates cancer cell growth, and found that Stathmin 1 levels were high in metastatic breast and prostate cancer." (PMID 40723207, 2025). "Our findings showed that JMJD2A promoted docetaxel resistance in prostate cancer cells by regulating cytoskeleton remodeling through the miR-34a/STMN1/β3-Tubulin axis." (PMID 37165308, 2023). "For example, Cluster 25 included STMN1 as a marker gene, a known over-expressed oncoprotein in prostate cancer that controls cell proliferation." (PMID 37449901, 2023). "JMJD2A promoted docetaxel resistance in prostate cancer cells by regulating cytoskeleton remodeling through the miR-34a/STMN1/β3-Tubulin axis." (PMID 37165308, 2023). "In prostate cancer, prostate-derived Ets transcription factor (PDEF) down-regulated oncogenic STMN1 expression to inhibit prostate cancer progression at transcription level." (PMID 34253824, 2021). "Inhibition of STMN1 expression in a prostate cancer cell line DU-145, a standard prostate cancer cell line used for CSC enrichment, accelerated the metastatic process by initiating an EMT program via activation of p38 and cooperation of TGF-β signaling." (PMID 33921319, 2021). "Down-regulation of miR-34a/b/c suppressed tumor formation in colorectal cancer, while over-expression of miR-34a in aggressive prostate cancers (PCAs) cells reduced proliferation and colony formation by CtBP1\miR-34a\STMN1\GDF15 pathway." (PMID 30319976, 2018). "We reported that freshly isolated primary prostate cancer (PCa) cells from patient prostate cancer (PCa) biopsy specimens and the NMuMG cell line expressed low endogenous levels of STMN1, and that these cells exhibited increased metastatic potential in vivo and in vitro, respectively." (PMID 40723207, 2025). "We aimed to analyze the changes in autophagy, invasion, apoptosis-related genes in prostate cancer (PCa) cell line (PC-3), after small interfering RNA (siRNA)-mediated STMN1 silencing, and also the relationships of STMN1 expression, clinicopathological parameters, and survival (OS) in PCa cases." (PMID 37529254, 2022). "Consistently, tumor suppressive roles of STMN1 were identified in prostate cancer cells." (PMID 33921319, 2021). "Similarly, knockdown of STMN1 in prostate cancer resulted in reduced proliferation and invasion of cells, tumor growth and metastasis." (PMID 34253824, 2021). "Functionally, it has been associated with the destabilisation and disassembly of microtubules and silencing stathmin 1 (using adenovirus technology) in combination with 5-FU was reported to increase apoptosis and decrease clonogenic survival of prostate cancer cells." (PMID 26878873, 2016). "Stmn1 (stathmin 1), a cellular protein involved in mictotubule destabilization, is over expressed in a wide variety of human cancers including liver, breast, lung and prostate cancer." (PMID 20959002, 2010). "In addition, the knockdown of JMJD2A resulted in significantly higher miR-34a and β3-Tubulin expression and lower STMN1 expression compared with the shNC group; consistent with the previously validated effects of the miR-34a/STMN1/β3-Tubulin axis on prostate cancer cells." (PMID 37165308, 2023).
prostate carcinoma (continued). "After determining that HGF is exogenously supplied to prostate cancer cells, the following experiments were performed to determine the impact of HGF/MET activity on the proliferation and phosphorylation of MET and STMN1." (PMID 40723207, 2025). "STMN1 expression was analyzed using cohorts that contain both AdPC and NEPC samples, including the Neuroendocrine Prostate Cancer dataset (Beltran Nat Med 2016 and SU2C 2019)." (PMID 39711570, 2024). "Specifically, it intensifies the progression of lung adenocarcinoma by targeting CADM1, promotes the progression of prostate cancer by targeting GRIM-19, and suppresses the proliferation and invasion of osteosarcoma by targeting STMN1." (PMID 38140218, 2023). "With the 5-gene prostate cancer metastasis signature panel comprised of U2AF2, RUVBL1, STMN1, HDGF, and FABP4, we further assessed the power of prediction of this gene signature panel in two different, independent public patient datasets (Grasso CS, Nature, 2012; Varambally S CS, Cancer Cell, 2005)." (PMID 39402324, 2024). "Indeed, most studies on the HGF/MET-mediated phosphorylation of STMN1 have not used prostate cancer cell lines, nor have they investigated in detail the regulation of both tSTMN1 and STMN1 phosphorylation during cell cycle progression." (PMID 40723207, 2025). "In DU-145 prostate cancer (PCa) cells, HGF is reported to increase proliferation; however, STMN1 phosphorylation is not evaluated in this landmark study (439 citations)." (PMID 40723207, 2025). "Knockdown of STMN1 in MPM cells did not block the anti-tumor activity of CIT-026, and STMN1 knockdown in prostate cancer cells did only partially block CIT-induced cell death." (PMID 37305581, 2023).
lung carcinoma (20 papers, 2008 to 2025). "Several studies verified that STMN1 was associated with worse survival rates for lung cancer patients." (PMID 36428585, 2022). "Subsequent studies have found that loss of RB1 renders lung cancer cells suspectable to microtubule destabilization due to overexpression of STMN1, a microtubule depolymerizing protein." (PMID 36372230, 2022). "Flowingly, PTEN loss promoted the stability of STMN1 after lung cancer cells were treated with CHX (cycloheximide, CHX)." (PMID 34253824, 2021). "Here, we found that STMN1 was overexpressed in lung cancer tissues and associated with worse survival rates of lung cancer patients." (PMID 34253824, 2021). "Taken together, these results suggested that STMN1 was overexpressed in lung cancer tissues and associated with worse survival rates of lung cancer patients." (PMID 34253824, 2021). "Finally, a prior publication showed that upregulation of the microtubule depolymerizing protein Stathmin 1 (STMN1) in RB1 deficient lung cancer cells created synthetic lethality with AURKA inhibition." (PMID 36372230, 2022). "PTEN loss in lung cancer regulated the expression and function of STMN1." (PMID 34253824, 2021). "Here we investigated the function of STMN1 gene in lung cancer and might molecular mechanism underlying lung cancer progression." (PMID 34253824, 2021). "For example, long noncoding RNA LINC00336 inhibits ferroptosis in lung cancer by functioning as a ceRNA, and miR-423-5p inhibits osteosarcoma proliferation and invasion through directly targeting STMN1." (PMID 38485945, 2024). "A study showed that downregulation of stathmin 1 reduced the malignancy of lung cancer cells and decreased the chemoresistance of cancer cells to paclitaxel." (PMID 37162289, 2023). "STMN1 contributes to cancer metastasis, and STMN1 RNA interference significantly inhibits lung cancer cell migration and invasion." (PMID 36188577, 2022). "These suggested that STMN1 as an oncogene was involved in lung cancer progression by regulating cell proliferation, migration and invasion." (PMID 34253824, 2021). "To investigate the mechanisms of STMN1 regulating lung cancer cell progression, we detected PI3K/AKT signaling pathway." (PMID 34253824, 2021). "Cell proliferation analysis of lung cancer illustrated that knockdown of PTEN ameliorated the effect of STMN1 knockdown inducing decreased cell proliferation when double RNA interferences of STMN1 and PTEN were performed." (PMID 34253824, 2021). "The expression level of STMN1 protein was also studied after lung cancer cells were treated with paclitaxel, and western blotting showed that paclitaxel decreased the STMN1 expression level." (PMID 34253824, 2021). "In conclusion, this study demonstrated that overexpression of STMN1 changed lung cancer cell growth, migration, invasion and drug sensitivity." (PMID 34253824, 2021). "Firstly, cell proliferation was conducted by cell counting kit-8 (CCK-8) assay, and we found that knockdown of STMN1 markedly suppressed the cell viability of lung cancer." (PMID 34253824, 2021). "The high expression of STMN1 was negatively correlated with the low expression of PTEN in lung cancer specimens." (PMID 34253824, 2021). "The results showed that silencing of STMN1 significantly inhibited lung cancer cell migration compared with control group." (PMID 34253824, 2021). "We found that overexpression of STMN1 changed lung cancer cell growth, migration, invasion and drug sensitivity." (PMID 34253824, 2021). "PTEN loss ameliorated the inhibition of cell growth, migration and invasion, and drug sensitivity induced by STMN1 knockdown in lung cancer." (PMID 34253824, 2021). "We found that lung cancer patients with high STMN1 expression had worse overall and disease-free survival rates, respectively." (PMID 34253824, 2021).
lung carcinoma (continued). "Our results showed that STMN1 expression was significantly up-regulated in lung cancer specimens compared with normal ones, however, PTEN expression was down-regulated in lung cancer specimens." (PMID 34253824, 2021). "Inhibition of STMN1 suppressed lung cancer cell growth, migration and invasion, and promoted drug sensitivity." (PMID 34253824, 2021). "We further study the role of suppressor gene PTEN in the mechanisms of STMN1 function in lung cancer." (PMID 34253824, 2021). "Inhibition of PTEN expression in lung cancer cells promoted the expression of STMN1 and p-AKT (Thr-308) protein activity." (PMID 34253824, 2021). "We observed that the inhibition of STMN1 suppressed lung cancer cell growth, migration and invasion and promoted drug sensitivity." (PMID 34253824, 2021). "Similar to esophageal cancer, STMN1 is highly expressed in various cancers, including leukemia, breast, prostate and lung cancer, and is a promising target for cancer therapy." (PMID 33828156, 2021). "Next, we evaluated the protein of STMN1 in lung cancer by western blotting and found that STMN1 protein level was higher than normal tissues." (PMID 34253824, 2021). "We found that PTEN loss promoted the expression level of STMN1 and knockdown of PTEN ameliorated the effect of STMN1 inhibition inducing the suppression of lung cancer cell function." (PMID 34253824, 2021). "To date, in available literature, there is only one publication that contains data on influence of any of the polymorphisms in the STMN1 gene (including −2166T>C, rs182455) on the effectiveness of any of the currently used CTH regimens in lung cancer." (PMID 26220844, 2015). "It has been reported that Stmn1 is overexpressed in many human malignancies, such as leukemia, lymphoma, neuroblastoma, ovarian, prostatic, breast and lung cancers." (PMID 23071542, 2012). "AKT/FOXM1/STMN1 axis in lung cancer also contributes to resistance to tyrosine kinase inhibitors." (PMID 38698443, 2024). "By using the expression pattern of signature genes identifying the N1 state (Tnf, Fas), the N2 state (Arg1, Ccl2), and immature neutrophils (Stmn1, Ube2c), pseudotime analysis confirmed the developmental direction of TANs with N2 as an early state of TANs in the lung cancer TME." (PMID 37002229, 2023). "High STMN1 expression was detected in lung cancer with low PTEN expression." (PMID 36188577, 2022). "Moreover, we observed that the high expression of STMN1 was negatively correlated with the low expression of PTEN in lung cancer specimens." (PMID 34253824, 2021). "Overall, our work demonstrated that PTEN regulated the oncogenic function of STMN1 in lung cancer." (PMID 34253824, 2021). "The effect of PTEN on STMN1 inducing lung cancer cell growth was further investigated." (PMID 34253824, 2021). "Next, we assessed the effect of STMN1 on sensitivity of lung cancer cells to cancer drug." (PMID 34253824, 2021). "Similarly, high expression of STMN1 has been reported to involve the proliferation, migration, and invasion of various cancer cells, among them were lung cancer and colorectal cancer." (PMID 34107874, 2021). "Furthermore, MG132 treatment together with knockdown of PTEN in lung cancer cells make STMN1 protein more stable." (PMID 34253824, 2021). "We found that the expression of STMN1 in lung cancer was higher than normal tissues." (PMID 34253824, 2021). "However, the molecular mechanism of STMN1 regulating lung cancer is still unclear." (PMID 34253824, 2021). "The measurement of STMN1 and GSTP1 proteins enabled the two main subtypes of lung cancer (non-small-cell and small-cell) to be distinguished with 57% specificity and 90% sensitivity." (PMID 36552956, 2022). "Wound healing assay showed that double knockdown of STMN1 and PTEN raised lung cancer cell migration compared with single knockdown of STMN1." (PMID 34253824, 2021).
lung carcinoma (continued). "Next, we also investigate the molecular mechanism regulating STMN1 and found that PTEN gene affected the expression and function of STMN1 in lung cancer." (PMID 34253824, 2021). "The STMN1 and PTEN mRNA expression levels in lung cancer specimens were detected by real time PCR." (PMID 34253824, 2021). "When lung cancer cell A549 and H1975 were treated with PI3K-kinase inhibitor LY294002 for 48 h, the results demonstrated that LY294002 increased the expression of PTEN and decreased the STMN1 and p-AKT protein levels." (PMID 34253824, 2021). "The correlation of STMN1 with PTEN was assessed and we found that there was a negative correlation between STMN1 and PTEN expression in lung cancer specimens." (PMID 34253824, 2021). "Of interest, the three tumor-related genes: tumor protein D52, melanoma antigen family D 4, stathmin 1/oncoprotein 18 and two oncogenes DEK oncogene and forkhead box G1 were upregulated which has not been described in the context of lung cancer so far." (PMID 18992152, 2008).
colorectal cancer (17 papers, 2012 to 2025). A primary or metastatic malignant neoplasm that affects the colon or rectum. "The miR-210 high expression and STMN1 low expression pattern (miR-210High/STMN1Low) correlated with liver metastasis and unfavorable prognosis in colorectal cancer patients, suggesting its potential as a prognostic marker." (PMID 40710326, 2025). "miR-210 diminishes the cellular rigidity of colorectal cancer stem cells (CRCSCs) by targeting Stathmin1 (STMN1), thereby enhancing their invasiveness, a process that is independent of epithelial–mesenchymal transition (EMT)." (PMID 40710326, 2025). "For example, the expression level of four genes, such as BAD, decreased in colorectal cancer, while the expression level of 28 genes, such as STMN1, increased in colorectal cancer." (PMID 38528462, 2024). "In colorectal cancer, STMN1 expression is also correlated with elevated cell proliferation and poorer patient prognosis in metastatic disease." (PMID 38893174, 2024). "Stathmin 1 (STMN1) was identified as a direct functional target of miR-193b in colorectal cancer." (PMID 31262974, 2019). "In colorectal cancer, LINC01116 was found to promote cancer progression through the miR-9-5p/STMN1 axis." (PMID 33762953, 2021). "Considering that the in vitro results of STMN1 and BAD in colorectal treatment were inconsistent, our results suggested that Fenticonazole may not provide a new therapeutic action in colorectal cancer and that it needed more research to be introduced as an anti-cancer drug." (PMID 38528462, 2024).
ovarian carcinoma (16 papers, 2014 to 2025). A malignant neoplasm originating from the surface ovarian epithelium. "Our findings in this study revealed that the expression of STMN1 was significantly higher in ovarian cancer tissues compared to normal tissues, which was associated with shorter overall survival." (PMID 41361792, 2025). "STMN1 was upregulated in ovarian cancer tissues as compared to paracancerous tissues and associated with shorter overall survival." (PMID 35186166, 2022). "The level of STMN1 expression was closely associated with pathological differentiation and clinical stage in patients with ovarian cancer." (PMID 35186166, 2022). "Consistently, STMN1 overexpression has been associated with poor prognosis of ovarian cancer patients receiving TX-based chemotherapy." (PMID 25897432, 2015). "Opposite to the high expression of STMN1, miR-31 negatively associated to chemoresistance in ovarian cancer tissues." (PMID 25897432, 2015). "However, the precise role and underlying mechanisms of STMN1 in the progression of ovarian cancer require further investigation." (PMID 41361792, 2025). "Besides, in the Kaplan-Meier survival curve analysis, the high expression of STMN1 was associated with poorer overall survival rates in the entire cohort of ovarian cancer patients." (PMID 41361792, 2025). "Overexpression of STMN1 is associated with paclitaxel resistance and survival in ovarian cancer." (PMID 35186166, 2022). "Nonetheless, the precise role of STMN1 in ovarian cancer and its clinical implications warrant further elucidation." (PMID 41361792, 2025). "Next, cell proliferation assays, CCK-8, and scratch wound assays were conducted to examine the effects of STMN1 on ovarian cancer cell proliferation." (PMID 41361792, 2025). "The results demonstrated that STMN1 expression was significantly higher in ovarian cancer tissues compared to normal ovarian tissues." (PMID 41361792, 2025). "E2F1 can promote the proliferation and migration of ovarian cancer cells by regulating stathmin 1 (STMN1) overexpression, and high STMN1 expression in ovarian cancer often indicates a poor prognosis." (PMID 38992083, 2024). "In summary, these results suggest that STMN1 is overexpressed in ovarian cancer tissues and that high expression indicates a poor prognosis." (PMID 35186166, 2022). "The effect and mechanism of STMN1 on the proliferation and migration of ovarian cancer cells were also investigated." (PMID 35186166, 2022). "To investigate the function of STMN1 in ovarian cancer, we transfected the siRNA or overexpression plasmid into ovarian cancer cells and measured cellular functions." (PMID 35186166, 2022). "The aim of this study was to investigate the expression of stathmin 1 (STMN1) in ovarian cancer and its effect on prognosis." (PMID 35186166, 2022). "In our study, we aimed to investigate STMN1 expression in ovarian cancer and correlated its expression with clinical factors and outcomes." (PMID 35186166, 2022). "The effect of STMN1 on ovarian cancer proliferation and migration was also confirmed through in vitro experiments." (PMID 35186166, 2022). "The effects of STMN1 on the proliferation and migration capacity of ovarian cancer were evaluated using Cell Counting Kit-8 (CCK-8) assays, colony formation assays, immunofluorescence staining, wound healing assays, and Transwell assays." (PMID 35186166, 2022). "We performed wound healing and Transwell assays to detect the effects of STMN1 on ovarian cancer cell migration." (PMID 35186166, 2022). "Downregulating STMN1 expression inhibited cell proliferation and migration of ovarian cancer cell lines, and upregulating STMN1 expression had the opposite effect." (PMID 35186166, 2022).